SIRT6 (sirtuin 6)
Diseases named in the same sentence as SIRT6 in open-access papers (continued):
Sharing a sentence is not in itself a finding about the gene and the disease.
diabetes (52 papers, 2011 to 2026). "The underlying mechanism through which Sirt6 modulates diabetes and glucose metabolism also underwent intensive investigations." (PMID 37497437, 2023). "For example, Sirt6 deficient mice developed different types of diseases and symptoms such as diabetes, osteoporosis, cancer, curved spines, lymphopenia and decreased subcutaneous fat, resembling a progeroid-like syndrome." (PMID 37497437, 2023). "In a mouse model with diabetes, they showed that SIRT6 deficiency reduced VEGF expression, increased the expression of pro-inflammatory markers (including TNF-α, IL-1β) and intensified oxidative stress when siRNA against SIRT6 was administered." (PMID 37298604, 2023). "In this study, we found that impaired efferocytosis and severe periodontal destruction occurred in diabetes-associated periodontitis due to deficient SIRT6 in macrophages." (PMID 36593966, 2023). "It has been shown that the activation of inflammatory cascade in diabetic atherosclerotic plaques, associated with lower SIRT6 levels, induce the expansion of oxidative and inflammatory processes in endothelial cells." (PMID 35328633, 2022). "In a recent study, hyperglycemia was shown to promote SIRT6 and TETs, in turn causing dynamic changes in 5 methyl cytosine and 5 hydroxy methyl cytosine in WBCs collected from diabetes mellitus type 2 (T2DM) patients." (PMID 34685528, 2021). "Because of SIRT6's pivotal role in maintenance of both genomic integrity and metabolic homeostasis, it is crucially important in cancer, diabetes, and other aging‐associated diseases." (PMID 34212132, 2021). "SIRT6 is recognized as an enzyme with multiple functions, influencing a wide range of diseases associated with cachexia such as cancer, diabetes, cardiovascular, and renal failure." (PMID 34212132, 2021). "As a regulator of gene expression, Sirt6 has been implicated in cancer, neurodegenerative diseases, heart diseases, diabetes, and aging-related processes." (PMID 33442387, 2020). "Sirt6 also mediates the effects of CR, which is known to delay the onset of age-associated diseases, including diabetes and cardiovascular diseases." (PMID 29535637, 2018). "The present study aims to investigate the diagnostic value of EMPs in diabetes and detect the protective effects of sirtuin 6 (Sirt6) mRNA -incorporated EMPs on endothelial dysfunction." (PMID 29371988, 2017). "To investigate potential changes in Sirt6 in pancreatic islets under diabetic conditions, we first analyzed Sirt6 expression levels in various pathologic conditions linked to diabetes." (PMID 27457971, 2016). "In addition, SIRT6 inhibits PPARγ expression at the transcriptional level and coordinates endothelial fatty acid uptake under pathological conditions to reduce diabetes-associated HF with preserved ejection fraction (HFpEF)." (PMID 38625851, 2024). "Increased SIRT6 levels may cause the opposite effect of SIRT6 deficiency, namely hyperglycemia, increasing the risk of diabetes with age as levels of SIRT6 and blood glucose rise." (PMID 33806509, 2021). "Therefore, maintaining the level or activity of Sirt6 is likely to be effective in preventing statin-induced risk of diabetes." (PMID 33052223, 2020). "Diabetes is often caused by β-cell dysfunction and recent studies have shown that SIRT6 may be important in glucose stimulated insulin secretion from these pancreatic β cells and SIRT6 may help improve insulin secretion in diabetics." (PMID 29966233, 2018). "Beyond the pancreas, physiological overexpression of SIRT6 enhances insulin sensitivity in skeletal muscle and liver, providing protection against type 2 diabetes mellitus." (PMID 41304967, 2025). "In the mouse diabetes model, it has been found that high glucose reduces the transfer of Sirtuin 6 (Sirt6) from the nucleus to the cytoplasm, leading to an increase in the acetylation level of Cav-1." (PMID 41030451, 2025).
diabetes (continued). "Previously, in the context of diabetes, SIRT6 in pancreatic β‐cells has been shown to regulate insulin secretion in response to glucose stimulation, reducing cellular dysfunction and apoptosis." (PMID 38967361, 2024). "In conclusion, our findings uncovered the essential role of the SIRT6-miR-216/217 axis in macrophage efferocytosis in the context of diabetes and outlined an approach to improve inflammation resolution and periodontium restoration using inhibition of miR-217." (PMID 36593966, 2023). "In this review, we examine the recent advances in understanding the mechanistic working through which Sirt6 alters the course of lethal cardiovascular diseases and diabetes mellitus." (PMID 37497437, 2023). "SIRT6 as a member of sirtuin family plays important roles in lifespan and diverse diseases, such as cancer, diabetes, inflammation and neurodegenerative diseases." (PMID 37542062, 2023). "Some people held that Sirt6 regulates glucose metabolism and diabetes mainly by targeting insulin resistance and pancreatic β cell function." (PMID 37497437, 2023). "In conclusion, these results indicated that Sirt6 exerts its beneficial leverage on diabetes by numerous signaling pathways." (PMID 37497437, 2023). "A role for SIRT6 in diabetic retinopathy (DR), one of the common microvascular complications of diabetes mellitus, has also been suggested during early neurodegenerative events that precede any detectable vascular changes." (PMID 38016059, 2023). "This indicates the involvement of SIRT6 in the inflammatory changes of atherosclerotic lesions in diabetes and the role of GLP-1 in modulating it." (PMID 37298604, 2023). "Accumulating evidence indicates that SIRT1 and SIRT6 are crucial players in chronic inflammation related to vascular homeostasis, cardiovascular disease, cardiac dysfunction and diabetes." (PMID 35328633, 2022). "In contrast, both high glucose levels in vitro and maternal diabetes in vivo significantly reduced the SIRT6 level in the embryo or neural stem cells." (PMID 36465178, 2022). "The controversy regarding activation or inhibition of SIRT6 activity as a therapeutic against type 2 diabetes mellitus stems from the idea that SIRT6 inhibition is able to prevent the repression of glucose transporters and enzymes." (PMID 36225477, 2022). "The protective effect of SIRT6 activating autophagy has been proved in different organ injuries, including I/R injury, diabetes, and sepsis." (PMID 36160707, 2022). "The results showed similar trends to EMT and tubular injury in Sirt6 knockdown mice, while a more severe pathology was observed in sh-FOXO3a groups, indicating the protective role of FOXO3a in diabetes-induced kidney injury." (PMID 34122724, 2021). "The potential application of these naturally occurring SIRT6 modulators in the amelioration of major human diseases such as Alzheimer’s disease, aging, diabetes, inflammation, and cancer has also been delineated." (PMID 33920726, 2021). "Henceforth, natural polyphenols that can regulate the activity of SIRT6 can be promising therapeutics for treating neurodegenerative diseases such as AD, aging, cancer, diabetes." (PMID 33920726, 2021). "It has been shown that the downregulation of sirtuin family members, such as SIRT1 and SIRT6, is closely related to the onset of insulin resistance and type 2 diabetes mellitus via inflammation and oxidative stress." (PMID 34073102, 2021). "SIRT6 action regulation compounds are thought to be potential drugs for age-related diseases, including obesity, diabetes, metabolic disorders, and neurological diseases." (PMID 33920726, 2021). "Studies in the recent past have also shown implications of Sirt6 in various diseases including dyslipidemia, diabetes, heart disease, cancer, neurodegenerative diseases, brain aging etc.." (PMID 33442387, 2020).
diabetes (continued). "This correlation between Sirt6 levels and glucose metabolism is a key in understanding involvement of Sirt6 in the pathogenesis in diabetes mellitus and a potential therapeutic target in the management of the disease." (PMID 33442387, 2020). "Until recently, Sirt6 was thought to regulate chromatin silencing, but new research indicates its role in aging, diabetes, cardiovascular disease, lipid metabolism, neurodegenerative diseases, and cancer." (PMID 33442387, 2020). "To explore the possible reasons for decreased 5mC and increased 5hmC in diabetes, we utilized qPCR to determine the mRNA expression of demethylation machinery genes and SIRT6 in diabetic patients and rats." (PMID 30987683, 2019). "Diabetes is a major human disease that is characterized by irregularities in glucose regulation and SIRT6 has been demonstrated to be a principal regulator of glucose homeostasis." (PMID 29966233, 2018). "The role of SIRT6 as a regulator or even a nutrient detector in cells has diversified its impact on aging-related processes and major human diseases such as cancer, diabetes, neurodegenerative diseases, and heart disease." (PMID 29966233, 2018). "Variants of the SIRT1, SIRT2, SIRT6, UCP1, UCP2, and UCP3 genes have been related to diabetes, obesity, serum high-density lipoprotein cholesterol (HDL), and inflammation." (PMID 22087257, 2011). "Additionally, myeloid-specific knockout of Sirt6 mice on a high-fat diet develops insulin resistance, a great liability for diabetes." (PMID 37497437, 2023). "Moreover, literature demonstrated that Sirt6 also maintains normal cardiac function and attenuates heart failure in mouse model of diabetes." (PMID 37497437, 2023). "Taken together, it seemed that Sirt6 influences many aspects of the etiology of diabetes." (PMID 37497437, 2023). "SIRT6 has many functions in regulating lifespan, and abnormal SIRT6 expression has been found to be involved in the pathogenesis of many health-threatening diseases, such as steatohepatitis, diabetes, tumors, neurodegenerative diseases, and cardiovascular diseases." (PMID 35677446, 2022). "Diabetic myocardial fibrosis is alleviated through SIRT6/AMPK signaling pathway." (PMID 36172184, 2022). "SIRT6 also regulates crucial proteins involved insugar homeostasis,as it promotes the expression of glycolytic genes, suppressing gluconeogenesis and increasing insulin secretion, hencehaving a favorable role in diabetes." (PMID 34213345, 2021). "SIRT6 activators effectively treat diabetes and promote longevity." (PMID 33920726, 2021). "Since the involvement of SIRT6 holds such promise, researchers are in the process of identifying SIRT6-targeted therapeutic agents that may have a wide range of uses in diabetes as well as several other diseases." (PMID 29966233, 2018). "This indicates that the role of Sirt6 in DNA damage may as a new therapeutic pathway for cancer and diabetes related disorders." (PMID 29535637, 2018). "Recently, it has been shown that Sirt2 and Sirt6 are involved in diabetes-induced NTDs." (PMID 28798665, 2017). "Combining these data, we may deduce that Sirt6 mRNA-incorporated EMPs may mediate an important mechanism in the transfer of information to neighboring and remote ECs in diabetes." (PMID 29371988, 2017). "Some interactions with a nominal p≤0.01 were found between sex and SNPs in the UCP1 and UCP3 gene; between smoking, diabetes, hypertension and SNPs in UCP5 and SIRT5; and between SNPs in the UCP5 gene and the UCP1, SIRT1, SIRT3, SIRT5, and SIRT6 genes in association with plaque phenotypes." (PMID 22087257, 2011). "Mice placed on caloric restriction or Sirt6 activators overexpress Sirt6, improving cancer, and age-related disorders in animal models, on the contrary, lower Sirt6 levels in mice showed shorter life expectancy, cancer occurrence, diabetes and other metabolic disorders increased." (PMID 33442387, 2020).
diabetes (continued). "Even until very recently, SIRT6 was known more for chromatin signaling but, being a nascent topic of study, more information has been ascertained and its potential involvement in major human diseases including diabetes, cancer, neurodegenerative diseases, and heart disease." (PMID 29966233, 2018). "Therefore, pharmacological activators of Sirt6 may be a promising therapeutic tool for promoting insulin secretion in patients with diabetes." (PMID 27457971, 2016). "Our data revealed that circulating SIRT6 levels were negatively correlated with FBG and the comorbidity of diabetes, which is consistent with previous findings." (PMID 39851250, 2025). "SIRT6 genotype does not influence the prevalence of scoliosis, hypertrophic cardiomyopathy, or diabetes in FRDA." (PMID 36133907, 2022). "In conclusion, diabetes leads to increased EMP release and decreased serum Sirt6 levels." (PMID 29371988, 2017).
cardiac hypertrophy (48 papers, 2015 to 2025). "Sirt6‐deficient mice develop severe concentric cardiac hypertrophy and exhibit rapid functional decline under certain genetic backgrounds." (PMID 41466491, 2025). "Other results indicated that Sirt6 blocks IGF signaling by interacting with c-JUN, inhibition of c-JUN or IGF signaling retards cardiac hypertrophy of Sirt6-deficient mouse hearts, thus preventing cardiac hypertrophy from progressing into heart failure." (PMID 37497437, 2023). "Then, literature is indicative of regulatory roles of Sirt6 in cardiac hypertrophy using loss-and-gain of function mouse models." (PMID 37497437, 2023). "SIRT6-deficient mice showed symptoms of myocardial hypertrophy and heart failure, and the expression of SIRT6 in failing human hearts was reduced." (PMID 35463332, 2022). "As an anti-senescence molecule, SIRT6 was shown to attenuate cardiac aging and aging-associated cardiac hypertrophy." (PMID 36465178, 2022). "We found that aging is associated with altered Sirt6 activity along with development of cardiac hypertrophy and fibrosis." (PMID 33934090, 2021). "Further, compared to wild-type mice, the hearts of Sirt6.Tg mice showed reduced expression of aging markers, and the development of aging-associated cardiac hypertrophy and fibrosis." (PMID 33934090, 2021). "Collectively these results indicate that hyperactive mTOR signalling contributes to increased protein synthesis and cardiac hypertrophy in SIRT6 deficient mice." (PMID 31372634, 2019). "We have previously demonstrated that SIRT6 deficiency in the heart leads to the development of cardiac hypertrophy." (PMID 31372634, 2019). "In the present study, we used this system to establish the link between mTOR signalling and cardiac hypertrophy under SIRT6 deficient conditions." (PMID 31372634, 2019). "Overall, these findings have unravelled a new layer of regulation of global protein synthesis by SIRT6, which can be potentially targeted to combat aging-associated diseases like cardiac hypertrophy." (PMID 31372634, 2019). "The fact that SIRT6 is a negative regulator of cardiac hypertrophy, which is further demonstrated in another study where SIRT6 deficient mice were compared to SIRT6 transgenic mice and the latter showed attenuated cardiac hypertrophy." (PMID 29966233, 2018). "Whilst SIRT6 has been implicated in the delay of ageing phenotype, DNA repair, and in the prevention of inflammation, ED and cardiac hypertrophy, SIRT7 is a major regulator of nuclear-encoded genes involved in mitochondrial function of cardiac cells." (PMID 29686722, 2018). "Sirt6 acts as a tumor suppressor and deficiency of Sirt6 leads to cardiac hypertrophy and heart failure." (PMID 27045575, 2016). "Moreover, SIRT6 functions as a key anti-aging molecule by controlling multiple cellular processes associated with aging and preventing age-induced cardiac hypertrophy and fibrosis." (PMID 38294557, 2024). "Additionally, a study reported of important roles of Sirt6 in regulating in cardiac hypertrophy associated with deubiquitinase ubiquitin-specific protease 10 (USP10)." (PMID 37497437, 2023). "Our data suggest that Sirt6 is a critical anti-aging molecule that regulates various cellular processes associated with aging and protects the heart from developing aging-induced cardiac hypertrophy and fibrosis." (PMID 33934090, 2021). "Since SIRT6 deficiency leads to enhanced protein synthesis by virtue of increased activation of mTOR signalling, we tested whether pharmacological inhibition of mTOR signalling can rescue cardiac hypertrophy observed under SIRT6 deficient conditions." (PMID 31372634, 2019). "For the reason that cardiac hypertrophy and inflammation are associated with myocardial fibrosis and injury, it is conceivable to think that SIRT6 is an antifibrotic and antiinflammatory sirtuin whose upregulation may help to impede the development of fibrosis- and inflammation-related diseases." (PMID 29069788, 2017).